PLN (phospholamban)
Diseases named in the same sentence as PLN in open-access papers (continued):
Sharing a sentence is not in itself a finding about the gene and the disease.
Duchenne muscular dystrophy (2 papers, 2018 to 2020). Duchenne muscular dystrophy (DMD) is a neuromuscular disease characterized by rapidly progressive muscle weakness and wasting due to degeneration of skeletal, smooth and cardiac muscle. "Recently, the CRSIPR/Cpf1-mediated dystrophin knock-out pigs, and phospholamban knock-in pigs with a 3-nt deletion in the presence of a single-stranded oligo donor, have been established as a Duchenne muscular dystrophy (DMD) and dilated cardiomyopathy (DCM) models, respectively." (PMID 30233645, 2018).
Hyperinsulinemia (2 papers, 2022). An increased concentration of insulin in the blood. "At the end of the clamp, proteins were isolated from hearts for PLN immunoblot and revealed a statistically increased phosphorylation of PLN at Ser16 in hearts subjected to hyperinsulinemia and isoproterenol exposure, relative to hearts that received isoproterenol alone." (PMID 36073057, 2022). "β‐adrenergic activation of phospholamban phosphorylation was not impaired by hyperinsulinemia." (PMID 36073057, 2022). "Considering how alterations in PDE activity may dysregulate SERCA2a activity, it was reported recently that hyperinsulinemia induces systolic and diastolic dysfunction by increasing expression of PDE4D, which contributes to reduced PKA mediated phosphorylation of PLN." (PMID 35621874, 2022).
infarction (2 papers, 2021 to 2023). A localised pathological necrosis of tissue resulting from obstruction of the blood supply usually by a thrombus, an embolus, or vascular torsion. "For instance, SERCA2a activity in myocardium derived from infarction sites is attenuated due to the decrease of phosphorylation of PLN." (PMID 36759868, 2023). "We have previously found that TH treatment in animal models of infarction-related HF results in activation of Akt, increased SERCA/phospholamban ratio and improved cardiac function." (PMID 34884213, 2021).
left ventricular hypertrophy (2 papers, 2021 to 2024). Enlargement of the LEFT VENTRICLE of the heart. "Finally, earlier versions of the Blueprint Genetics HCM panel did not include the now well-established HCM/left ventricular hypertrophy genes PLN and PTPN11, which might also have an impact on overall yield." (PMID 33673806, 2021).
lymph node metastasis (2 papers, 2024 to 2025). "In this study, we assembled a cohort of primary OSCC with and without lymph node metastasis (pLN+ and pLN–) and performed multi‐omics, single‐cell, and spatial analyses to delineate the mechanisms associated with LNM in OSCC." (PMID 40038875, 2025). "To establish the genomic landscape, we conducted whole‐exome sequencing (WES) of primary OSCC samples without lymph node metastasis (pLN–) (n = 35) and with lymph node metastasis (pLN+) (n = 6)." (PMID 40038875, 2025).
muscular dystrophy (2 papers, 2019 to 2023). Muscular dystrophy (MD) refers to a group of more than 30 genetic diseases characterized by progressive weakness and degeneration of the skeletal muscles that control movement. "Importantly, PLN-TG mice show muscular dystrophy, including severe muscle wasting, fibrosis, fatty infiltration and muscle weakness." (PMID 30986276, 2019).
ventricular dilatation (2 papers, 2022 to 2024). "Mutations in certain regions of the phospholamban (PLN) gene, such as the deletion of Arg 14 (R14 del), are commonly associated with malignant arrhythmias and ventricular dilatation." (PMID 38974714, 2024).
advanced heart failure (1 paper, 2024). Patients with advanced heart failure have severe limitations, experiences symptoms even while at rest and are mostly bedbound patients. "An in vitro study assessed the effectiveness of an ASO directed at PLN, reducing its impact on SERCA2a in heart cells obtained from nine individuals suffering from advanced heart failure." (PMID 39684857, 2024).
atrioventricular block (1 paper, 2024). A heart block that is initiated in the atrioventricular node. "DCM patients with mutations in LMNA, PLN, RBM20, FLNC, DES, or SCN5A are associated with typical cardiac rhythm disorders ranging from atrioventricular blocks to supraventricular and malignant ventricular arrhythmias (MVA)." (PMID 39070560, 2024).
breast carcinoma (1 paper, 2023). "Neuronatin (NNAT) is a small proteolipid (9kD) with high sequence homology to phospholamban, which was also recently identified as a novel modifier of estrogen receptor-positive (ER+) breast cancer incidence and survival." (PMID 37400769, 2023). "Based on high protein homology with phospholamban, we hypothesized that NNAT mediates the homeostasis of intracellular calcium [Ca2+]i levels and endoplasmic reticulum (EndoR) function, which is frequently disrupted in ER + breast cancer and other malignancies." (PMID 37400769, 2023).
cardiac arrest (1 paper, 2024). Cessation of breathing and/or cardiac function. "A 14-year-old female cardiac arrest survivor was found to harbor the same nonsense variant in PLN in a heterozygous state, as well as a 57-year-old female with non-penetrant disease." (PMID 39273332, 2024).
chronic kidney disease (1 paper, 2016). Impairment of the renal function secondary to chronic kidney damage persisting for three or more months. "Thus, phospho-phospholamban may play a role in progression of chronic kidney disease." (PMID 27775022, 2016).
congenital heart disease (1 paper, 2012). A heart disease that is present at birth. "The present findings suggest regulating PLN phosphorylation by inhibiting PP1 may improve cardiac function when the right heart failure occurs in cyanotic congenital heart diseases with RVH." (PMID 22472319, 2012). "Because the adverse effect was induced by a combination of hypoxia and hypertrophy, correcting hypoxia by early surgical repair may recover the phosphorylated state of PLN and contribute to the improved cardiac contractility in cyanotic congenital heart diseases with RVH." (PMID 22472319, 2012).
depression (1 paper, 2019). "Conversely, high levels of LMR were significantly negatively associated with advanced TNM, pLN, and occurrence of depression." (PMID 31396300, 2019). "Univariate Cox regression analysis indicated that pLN, TNM, and depression were associated with OS of patients with GC." (PMID 31396300, 2019). "Moreover, as inflammation markers, high levels of NLR were significantly positively related with advanced TNM, pLN, and occurrence of depression." (PMID 31396300, 2019).
Desminopathy (1 paper, 2025). "Less frequent but notable associations include DES (linked to desminopathy), PLN, SCN5A, and TNNC1, the latter contributing to the DCM phenotype in a smaller subset of patients." (PMID 39857686, 2025).
endometrioid tumor (1 paper, 2024). A benign, borderline, or malignant epithelial tumor of the female reproductive system characterized by the presence of glands and/or cysts lined by neoplastic cells that resemble endometrial cells. "In patients with endometrioid tumors, PLN+PAN- and PLN-PAN+ exhibited a similar better prognosis than PLN+PAN+ in stage IIIC disease." (PMID 39544303, 2024).
eosinophilic esophagitis (1 paper, 2024). Eosinophilic esophagitis (EoE) is a chronic, allergic disease of the esophagus characterized clinically by symptoms of esophageal dysfunction (including vomiting, dysphagia, feeding disorders, food impaction and abdominal pain) which persist after treatment with proton pump inhibitors (PPIs). "In the type 2 inflammatory disorder, eosinophilic esophagitis (EoE), phospholamban (PLN) can induce smooth muscle cell hypertrophy." (PMID 38423390, 2024).
fibrosis (1 paper, 2020). the formation of excess fibrous connective tissue in an organ or tissue in a reparative or reactive process. "The cardiac dysfunction is mediated by increased PLN phosphorylation at threonine 17 and serine 16, as well as inhibition of Akt/mTOR signaling and autophagic activity, leading to cardiac fibrosis, cardiac myocyte apoptosis, and oxidative stress." (PMID 32716920, 2020).
gastrointestinal stromal tumor (1 paper, 2022). "Our analysis and further experimental verification show that circTBC1D4 promotes the progression of gastrointestinal stromal tumor by regulating miR-590-5p/PLN axis in GIST, providing new insights for GIST." (PMID 35655923, 2022). "Furthermore, the results revealed that two of the four central DEGs (ATP1A2, PLN, KCNMA1, and SCNN1B) of the PPI network were created in this module, thus suggesting that PLN and ATP1A1 may have a significant important role in gastrointestinal stromal tumors." (PMID 35655923, 2022).
Iron deficiency anemia (1 paper, 2019). "Remodeling of cardiac Ca2+ signals in iron-deficiency anemia relates to downregulated RyR2 channels and dephosphorylation of the SERCA regulator phospholamban." (PMID 30779710, 2019). "However, PLN phosphorylation at Thr17 (but not Ser16) was reduced 2-fold in iron-deficiency anemia, which predicts a stronger inhibitory influence on SERCA." (PMID 30779710, 2019).
kidney damage (1 paper, 2016). "In order to identify phosphoproteins that may play a role in salt-induced kidney damage, we examined changes in phosphorylation levels of lamin A and phospholamban as well as their downstream genes desmin and SERCA2a, which altered significantly in response to high salt intake in 5/6Nx rats." (PMID 27775022, 2016).
laminopathies (1 paper, 2025). "Notably, a dedicated risk score for life-threatening ventricular tachyarrhythmias has been developed for laminopathies and phospholamban (PLN) variant carriers." (PMID 39941414, 2025).
limb ischemia (1 paper, 2023). A ischemia that involves the limb. "Finally, we tested if ABCB5+ MSCs restore ER Ca2+ using the Sarco-/endoplasmic reticulum ATPase 2a (SERCA2a)- Phospholamban (PLN) axis in both in-vitro cell models as well as in-vivo hind limb ischemia model in Apolipoprotein E knock-out (ApoE−/−) mice, which model chronic on acute hypoxia." (PMID 36759868, 2023).
lung carcinoma (1 paper, 2025). "In conclusion, PLN-5 is a potent dual-target inhibitor of PLK1 and NRP1 and is expected to be further developed for the treatment of lung cancer." (PMID 40820676, 2025).
multisystemic smooth muscle dysfunction syndrome (1 paper, 2024). A spectrum of conditions caused by monoallelic pathogenic variants in ACTA2. "The gene ontologies for list 5+ linked FOXF1, KCNMB1, MYH11, and PLN to Multisystemic Smooth Muscle Dysfunction Syndrome." (PMID 39480826, 2024). "No literature was located directly linking PLN (phospholamban) to Multisystemic Smooth Muscle Dysfunction Syndrome." (PMID 39480826, 2024).
oral cancer (1 paper, 2020). "In conclusion, none of the 100 patients diagnosed as cN1 oral cancer had pLN to level V, suggesting that level V dissection can be excluded." (PMID 32140953, 2020).
osteosarcoma (1 paper, 2022). A usually aggressive malignant bone-forming mesenchymal neoplasm, predominantly affecting adolescents and young adults. "NLR and PLN levels have been indicated to be of certain predictive value for the clinical progression and prognosis of patients with osteosarcoma." (PMID 35070222, 2022).
pneumococcal pneumonia (1 paper, 2008). A febrile disease caused by STREPTOCOCCUS PNEUMONIAE. "Considering that especially low TNF-α concentrations in the lungs early after induction of pneumococcal pneumonia are important for limiting the growth of S. pneumoniae, this differential response may have contributed to the enhanced growth of S. pneumoniae PLN in TLR2 KO mice." (PMID 17711480, 2008).
primary cardiomyopathies (1 paper, 2024). "Both the inhibition and overexpression of phospholamban have been associated with the development of primary cardiomyopathies in humans." (PMID 38392255, 2024).
rectal cancer (1 paper, 2023). A primary or metastatic malignant neoplasm that affects the rectum. "Among the 114 patients with rectal cancer, 38 (33.3%) showed pLN, 13 (11.4%) showed postoperative distant metastases and 17 (14.9%) showed pathologically confirmed TDs." (PMID 37671062, 2023).
renal failure (1 paper, 2018). "In our model of renal failure, both SERCA2a protein expression and phosphorylation status of PLN were not changed, indicating that these cannot explain the declined velocity of calcium reuptake into the SR." (PMID 29611320, 2018).
type-2 diabetes (1 paper, 2021). "In preclinical animal models of both type-1 and type-2 diabetes, a reduction in the expression and activity of the Ca2+ handling protein, sarcoplasmic/endoplasmic reticulum Ca2+-ATPase (SERCA2a), and/or an increase in its regulator, phospholamban (Pln), impairs cardiac function." (PMID 34076247, 2021).
cardiac disease (17 papers, 2010 to 2025). "More research on the characteristics of the different types of human PLN mutations is needed to understand their effects on the etiology of heart diseases." (PMID 37534277, 2023). "Mouse models for DCM-associated PLN pathogenic variants provide sufficient evidence to support a disease-causing role of PLN pathogenic variant in cardiac disease." (PMID 29119312, 2017). "PLN is primarily associated with heart disease, but abnormalities in calcium regulation could affect smooth muscle function in arterial walls, thereby indirectly influencing the risk of AAA." (PMID 39600608, 2024). "Since the PLN-R14del pathogenic variant is the root cause of this heart disease, elimination of PLN expression can be considered a very promising therapeutic approach, providing a great example of a potential personalized medicine for PLN-R14del carriers." (PMID 35269571, 2022). "Phospholamban (PLN) is a key regulator of cardiac muscle contractility and has become a central focus in the study of cardiac disease." (PMID 40556736, 2025). "The present study has compiled information from all published PLN variants as well as in-depth analysis of the reported PLN variants in the ClinVar and gnomAD genetic databases, revealing the complex genetic contribution of PLN to cardiac disease." (PMID 40556736, 2025). "These advances underscore the importance of recognizing PLN’s role in cardiac disease and the value of genetic testing for accurate diagnosis, prognosis, effective management, and early risk prediction for family members." (PMID 40556736, 2025). "Identifying which treatment strategies are capable of efficiently targeting and restoring the heart will also make promising treatment strategies for other genetic heart disease, beyond PLN R14del." (PMID 35699837, 2022). "Expression of calcium regulatory proteins is commonly altered in heart disease, and, similarly, PLN expression gradually decreased over time in PLN-R14 Δ/Δ mice." (PMID 35269571, 2022). "PLN R14del is a great opportunity to optimize the workflow of precision medicine in genetic heart disease, due to the monogenetic nature and large patient population." (PMID 35699837, 2022). "For four of these loci, the top gene according to OPEN had been shown to be mutated in DCM (PLN, ACTN2, TNNT2, TTN), while for two others, the top gene was known to be mutated in HCM (MYL2) or an arrhythmogenic form of cardiac disease (CASQ2)." (PMID 25633252, 2014). "Different genes have been found to be related to ALVC, and the more frequent are Desmoplakin (DSP), Filamin C (FLNC), Phospholamban (PLN), and Desmin (DES); however, there is a prevalence of variants of genes already known to be related to inherited cardiac disease and of gene-elusive cases." (PMID 35893404, 2022). "SERCA2a and DWORF overexpression are examples of PLN-related signal transduction modulation that show beneficial effects in heart disease that require fine tuning, but may be a promising therapeutic for future PLN R14del studies." (PMID 35699837, 2022). "Due to this, modulating PLN is expected to have beneficial properties in heart disease." (PMID 35699837, 2022). "In addition, pre-emptive depletion of PLN using a PLN-ASO demonstrated beneficial effects in three murine models of heart disease." (PMID 35269571, 2022). "Until then, other modalities that show promise such as PLN-ASOs and PLN siRNAs make great alternatives as a treatment strategy for genetic heart disease, as they have proven to be an effective treatment for PLN R14del and other etiologies of heart disease in vivo and in vitro [51, 52, 53, 54•]." (PMID 35699837, 2022). "PLN-ASO treated PLN R14Δ/Δ mice slowly progressed to HF, with first signs of cardiac disease at T19, which corresponds to the age of 22 weeks." (PMID 34462437, 2021).
cardiac disease (continued). "Furthermore, mutations in non-desmosomal genes, including Transmembrane protein 43—luma (TMEM 43), Phospholamban (PLN), Filamin C (FLNC), Desmin (DES), and LMNA (Lamin A/C), have been identified as contributing to the pathogenesis of heart disease." (PMID 40361967, 2025). "Therefore, we were also interested in assessing PLN-ASO effects in a cardiac disease model where calcium handling is impaired, but where PLN is not believed to be the direct instigator of disease." (PMID 34462437, 2021).